VWF (von Willebrand factor)
Diseases named in the same sentence as VWF in open-access papers (continued):
Sharing a sentence is not in itself a finding about the gene and the disease.
hemorrhage (11 papers, 2017 to 2025). Loss of blood from the vascular compartment to the exterior or into nonvascular body space as a result of rupture or severance of the blood vessels. "Hemostatic drugs such as tranexamic acid (an antifibrinolytic) and desmopressin (a von Willebrand factor-releasing drug) have also shown effectiveness in hemorrhage prophylaxis." (PMID 41303268, 2025). "The ultra-long length of the blood plasma protein von Willebrand factor (VWF) enables its activation by hydrodynamic forces at sites of hemorrhage (Springer, 2014)." (PMID 35532124, 2022). "Another platelet marker GPIIb/IIIa belongs to the large family of integrin complexes and plays a critical role in platelet aggregation and increased binding to plasma fibrinogen and endothelial von Willebrand factor, therefore, facilitating thrombin generation and blocking hemorrhage." (PMID 38888546, 2024). "All 3 VWD categories were associated with increased likelihood of hemorrhage compared with unknown VWD status (low VWF vs unknown: OR, 3.2 [95% CI, 1.9-5.5]; P < .001; normal VWF vs unknown: OR, 4.4 [95% CI, 3.5-5.6]; P < .001; and disease vs unknown: OR, 3.9 [95% CI, 0.8-18.3]; P < .001)." (PMID 32232448, 2020). "Type O blood was not a risk factor associated with hemorrhage after tonsillectomy with or without adenoidectomy despite lower baseline von Willebrand factor antigen and von Willebrand factor ristocetin-cofactor values in children with BT O vs those with non-O BT in our study cohort." (PMID 32232448, 2020). "Based on the VWF multimer analysis, it is desirable to develop safe TA-TMA therapy from the viewpoint of both hemorrhage and thrombosis." (PMID 39247211, 2024). "Interestingly, two proteins (uPA and PRTN3) in the CB group and three proteins (vWF, uPA, and EPHB4) in the RB group were also the significant proteins selected by LASSO logistic regression and random forest, among which only PRTN3 was related to hemorrhage and coagulation in the RF group." (PMID 36704472, 2022).
hemostatic disorder (11 papers, 2016 to 2025). "Prior to elective surgery all patients with suspected hemostatic disorders should visit a specialist for hemostasis allowing the diagnosis of severe VWD via the determination of VWF activity (GP1bM; GP1bR)." (PMID 30630422, 2019). "VWD is recognized as a hereditary hemostatic disorder stemming from the aberration of the gene residing on chromosome 12 that is essential for the synthesis of von Willebrand factor (VWF), a large multimeric glycoprotein constantly produced by endothelial cells and megakaryocytes." (PMID 41356103, 2025). "To evaluate the role of plasma VWF in the hemostatic disorder evoked by B. jararaca envenomation and the participation of botrocetin therein, we determined VWF antigen levels, VWF multimeric distribution (by discontinuous SDS-agarose electrophoresis) and VWF collagen-binding activity in plasma." (PMID 34478462, 2021).
unstable angina (11 papers, 2009 to 2025). "It was demonstrated in a prospective multicentre study involving 3,043 patients with stable angina or previous MI that higher plasma VWF levels were associated with an 8.5% higher rate of MI and sudden cardiac death." (PMID 36684571, 2022). "Another study suggested that the coronary plaque burden was associated with VWF: Ag levels in stable angina patients (SAP) undergoing coronary angiography." (PMID 36684571, 2022). "Early administration of atorvastatin in normocholesterolemic patients with unstable angina significantly affects von Willebrand factor (vWF) levels and liver-derived components of the thrombosis and fibrinolysis systems." (PMID 41375704, 2025). "In contrast, peptides from the plasma of patients with progressive unstable angina suppress the secretion of endothelin-1 by HEPCs, while the secretion of both von Willebrand factor and tissue plasminogen activator was increased." (PMID 36837440, 2023). "In unstable angina (UA) patients with the tendency of thrombogenicity increases if the proportion between VWF and ADAMTS13 changes significantly." (PMID 32095288, 2020). "A prospective multicenter study comprising 3043 patients with stable angina or previous MI, showed that the higher plasma levels of vWF correlated with an 8.5% increase in the rate of MI and sudden cardiac death." (PMID 33096906, 2020). "In the ESSENCE trial, vWF was investigated along with several other factors in patients with unstable angina and q-wave infarction." (PMID 22708908, 2012). "In unstable angina patients ADAMTS13 were lower compared with stable angina and showed an inverse correlation between ADAMTS13 and VWF." (PMID 32095288, 2020). "The main findings of this clinical study are that in patients with unstable angina, trimetazidine treatment prevented the increase in CK-MB, cTnI, and vWF and the decrease in NO induced by PCI but did not significantly affect the levels of h-FABP." (PMID 31565429, 2019). "Stable and unstable angina incidence did not correlate with the plasma levels of vWF." (PMID 33096906, 2020). "The authors concluded that patients presenting with unstable angina (UA) or non-ST elevation MI (NSTEMI) who experienced the composite endpoint of death, recurrent angina, MI, or revascularization at 14 days had on average double the vWF level as those who did not." (PMID 22708908, 2012).
aortic valve stenosis (10 papers, 2017 to 2025). Aortic valve stenosis (AVS) is a condition characterized by narrowing of the heart's aortic valve opening. "Increased shear stress, as seen in ventricular assist devices (VADs), total artificial hearts and aortic valve stenosis, has been reported to cause alterations in the configuration of vWF and reduced levels of high-molecular-weight multimers (HMWM) of vWF." (PMID 28754139, 2017). "Shear stress through aortic valve stenosis leads to hypoxia and conformational changes in vWF, modifications that contribute to the formation of ADs." (PMID 39124781, 2024). "The incidence of acquired VWD is not at all uncommon; one study showed that 79% of patients with severe aortic valve stenosis had decreased levels of high molecular weight VWF multimers." (PMID 36127959, 2022). "In contrast to patients with aortic valve stenosis undergoing TAVR only little data exist regarding vWF function in patients with mitral valve regurgitation treated by transcatheter mitral valve repair (TMVR)." (PMID 33372698, 2021). "Bivariate Pearson correlation was performed for baseline markers of vWF function (vWF:Ac, vWF:Ag and WF:Ac/vWF:Ag ratio) with different markers of aortic-valve-stenosis severity (aortic valve area, peak velocity, mean and max pressure gradients)." (PMID 31359325, 2019). "We used a recently introduced new vWF test method and, hence, did not use the same methodology described as correlated with valve shear stress and with aortic valve stenosis." (PMID 39200749, 2024).
autoimmune disease (10 papers, 2012 to 2025). A disorder resulting from loss of function or tissue destruction of an organ or multiple organs, arising from humoral or cellular immune responses of the individual to their own tissue constituents. "AvWS arises from underlying conditions like CKD, malignancies, or autoimmune diseases, which affect vWF function and levels." (PMID 39219970, 2024). "Idiopathic TTP is an autoimmune disease caused by severe deficiency of the von Willebrand factor (VWF) cleaving protease, a disintegrin-like and metalloprotease with thrombospondin type 1 repeats (ADAMTS13), due to inhibitory anti-ADAMTS13 antibodies." (PMID 26022055, 2015). "Inflammatory reactions of various kinds, such as infection, malignancy, and autoimmune diseases, also generally show increased fibrinogen activity and increased VWF antigen concentrations." (PMID 39336896, 2024). "Accordingly, infected HLA-DRB1*03:01 or HLA-DRB3*01.01 positive individuals may develop high affinity anti-RGD motif antibodies that react with the RGD motif in the host proteins, like fibrinogen, thrombin or von Willebrand factor, affecting haemostasis or participating in autoimmune disorders." (PMID 37492575, 2023).
colorectal cancer (10 papers, 1995 to 2022). A primary or metastatic malignant neoplasm that affects the colon or rectum. "A decrease in VWF expression is associated with improved survival in patients with colorectal cancer and liver metastases, and a single nucleotide polymorphism in VWF (rs73049469) is associated with overall survival in NSCLC." (PMID 33671634, 2021). "Additionally, ST3GAL6-AS1 was co-expressed with a variety of mRNAs, including PECAM1, VCAM1, CXCL12, CD34, CDH5, and VWF, and was associated with colorectal cancer progression." (PMID 33790949, 2021). "A more recent study evaluated this concept further and found that reduced ADAMTS13 activity and higher VWF antigen levels are associated with metastatic disease and reduced event-free survival, independent of age, gender, and stage-independent predictors of mortality in colorectal cancer." (PMID 35327035, 2022). "In colorectal cancer, a high plasma VWF concentration was identified as an independent prognostic factor by multivariate analysis, correlating with advanced disease and poor prognosis in patients with metastatic disease." (PMID 35327035, 2022). "Particularly high VWF levels were observed in pancreatic, lung, brain, stomach, and colorectal cancer patients and in those with distant metastases." (PMID 31294335, 2019). "Similarly, in colorectal cancers, increased density of vWF positive microvessels was found in cancers of higher tumor grade." (PMID 29299165, 2017). "This is in keeping with observations on invasive tumours (colorectal carcinoma) where vWF immunostaining has been found to be absent from some of the capillaries in the tumour." (PMID 11953822, 2002). "However, another human study of patients with colorectal cancer observed higher numbers of vWF-positive microvessels and a striking absence of macrophages in the tumor tissues, and suggested a positive association between these findings and poor clinical outcome." (PMID 25886574, 2015).
dengue (10 papers, 2012 to 2025). "Syntaxin-binding protein 5 (STXBP5), expressed in endothelial cells and platelets, has emerged as a candidate; its deficiency elevates P-selectin and von Willebrand factor (vWF), promoting pathological platelet adherence, a hallmark of severe dengue." (PMID 41583452, 2025). "The notion that the AB blood group is associated with a higher risk for severe dengue supports a role for VWF in dengue pathogenesis, since blood group AB is associated with higher VWF levels." (PMID 22563509, 2012). "In conclusion, severe dengue is associated with exocytosis of WPBs with consumption of VWF and low ADAMTS-13 activity levels." (PMID 22563509, 2012). "We first show that dengue is associated with increased binding of VWF to platelets." (PMID 30849118, 2019). "Plasma concentrations of AST, ALT and vWF as well as relative lymphocytes count, aPTT and TT were higher in the dengue group." (PMID 32544159, 2020). "Studies on dengue patients indicate endothelial injury and/or activation by increased concentrations of von Willebrand factor (vWF)." (PMID 32544159, 2020). "Our data demonstrate that excessive binding of VWF to platelets in dengue results in neuraminidase-mediated platelet desialylation and platelet clearance." (PMID 30849118, 2019). "We observed a significantly (P<0.001) higher binding of VWF to circulating platelets of patients in the acute or critical phase of dengue compared to healthy controls (gating strategy shown in S2 Fig)." (PMID 30849118, 2019). "It is also in concordance with our earlier observations that VWF:Ag is being consumed in children with severe dengue." (PMID 30849118, 2019). "In contrast to our current findings, VWF:Ag levels in these children admitted to the ICU with severe dengue showed an increasing trend towards discharge, while levels of VWF:propeptide decreased." (PMID 30849118, 2019). "We and other groups have previously shown that patients with acute dengue have higher VWF plasma levels." (PMID 30849118, 2019). "We have previously shown that the plasma of children with severe dengue contains increased levels of circulating VWF in an active–platelet binding–conformation and increased VWF proteolysis." (PMID 30849118, 2019). "Here, we show that platelets from patients with acute dengue have bound more VWF and have lost sialic acid from their membrane." (PMID 30849118, 2019). "Levels of TNF-α, thrombomodulin and VWF were significantly increased in the two dengue groups than in healthy controls, but similar between patients with and without bleedings." (PMID 23890510, 2013). "We demonstrated that severe dengue in Indonesian children is associated with a strong increase in plasma levels of the WPB constituents von Willebrand factor (VWF), VWF propeptide and osteoprotegerin (OPG)." (PMID 22563509, 2012). "The aim of this study was to characterize WPB exocytosis and changes in factors involved in VWF-platelet interaction in patients with severe dengue." (PMID 22563509, 2012). "Spearman correlation (r) of VWF-related variables with laboratory and clinical parameters of dengue severity." (PMID 22563509, 2012). "On D0, median plasma concentrations of fibrinogen and albumin as well as WBC absolute and neutrophils relative counts were decreased, whereas concentration of TAT, DD, AST, ALT, vWF and sST2 were elevated in the dengue group before defervescence compared to the OFI group." (PMID 32544159, 2020). "Plasma levels of active VWF levels are increased in patients with dengue, but it is unknown whether this results in higher binding of VWF to platelets." (PMID 30849118, 2019). "In two observational cohort studies in Bandung and Jepara, Indonesia, we show that adult patients with dengue not only had higher plasma concentrations of plasma VWF antigen and active VWF, but that circulating platelets had also bound more VWF to their membrane." (PMID 30849118, 2019).
dengue (continued). "The resulting VWF-mediated platelet clearance may in turn contribute to the vascular leakage syndrome that is characteristic of severe dengue." (PMID 30849118, 2019). "Together, this suggests that VWF is being consumed during severe dengue." (PMID 22563509, 2012). "In the post-defervescence phase, dengue patients had decreased albumin and fibrinogen median plasma concentration, a decreased PT, an increased TT as well as elevated AST, ALT, vWF plasma concentration and relative lymphocytes count." (PMID 32544159, 2020). "We therefore support the use of blood coagulation biomarkers (such as coagulation times, Fibrinogen, TAT complex, vWF, and DD), often not considered, to define severity end points in future dengue studies." (PMID 32544159, 2020). "In the current study, VWF consumption was probably less pronounced as most participants had dengue disease without severe complications." (PMID 30849118, 2019).
endocarditis (10 papers, 2020 to 2024). Inflammation of the endocardium. "A similar disease mechanism has been demonstrated in an S. aureus endocarditis model, as the local inflammation of cardiac valves causes endothelial activation and vWF release, which recruits platelet accumulation and captures S. aureus to the valve surface." (PMID 33203754, 2020). "And in Staphylococcus and Streptococcus pneumonia infections (such as endocarditis), vWF mediates the interaction between bacteria and vascular endothelium." (PMID 39654219, 2024). "It has been established that S. aureus binding to von Willebrand factor allows adherence to endothelial tissue and resistance to sheer forces, which are essential for the early stages of endocarditis." (PMID 37154710, 2023). "VWF strings also mediate pathological processes such as tumor metastasis, endocarditis, and microangiopathies." (PMID 32881285, 2020). "Indeed, in patients with inflammation-induced endocarditis who develop a catheter infection, or in intravenous drug users, for example, VWF is released following activation of endothelial cells, leading to platelet adhesion to the valve surface." (PMID 37108707, 2023). "The vWF is a huge multimeric human protein that triggers platelet adhesion in areas of vascular damage, which may favor endocarditis when present in pathogens due to platelet and fibronectin recruitment." (PMID 32296407, 2020).
prostate carcinoma (10 papers, 1998 to 2024). A carcinoma that arises from epithelial cells of the prostate gland. "The patient in the present study also had refractory hematuria after transurethral biopsy for suspected prostate cancer 5 years before the hepatectomy, even with the appropriate administration of VWF/factor VIII." (PMID 38926208, 2024). "VWF is also upregulated in androgen-independent prostate cancer cells." (PMID 33671634, 2021). "In a preclinical model of spontaneous prostate cancer, tumor growth was significantly suppressed in CXCR2-deficient mice compared with controls, with a corresponding reduction in tumor angiogenesis as measured by von Willebrand factor RNA expression." (PMID 30800123, 2019). "As observed with the breast and prostate cancer cell lines, a substantial increase in NCI-H460 cell death occurred in the UMCD6-treated compared to the anti-vWF–treated cocultures." (PMID 33497367, 2021). "In alignment with this hypothesis, in a preclinical model of spontaneous prostate cancer, tumor growth was significantly increased in CXCR3-deficient mice compared with controls, with a corresponding increase in tumor angiogenesis as measured by von Willebrand factor RNA expression." (PMID 30800123, 2019). "vWF IHC staining represents an effective maker of MVD, and as such has been suggested that as a useful prognostic marker for colorectal, ovarian and prostate cancers’ progression and/or patient survival." (PMID 25886574, 2015).
acute kidney injury (9 papers, 2011 to 2025). Sudden and sustained deterioration of the kidney function characterized by decreased glomerular filtration rate, increased serum creatinine or oliguria. "Patients with severe hepatic encephalopathy, systemic inflammatory response syndrome, or acute kidney injury had the lowest levels of ADAMTS-13 combined with the highest levels of VWF." (PMID 37443746, 2023). "Similarly, rhADAMTS13 counteracted oxidative stress in an experimental model of acute kidney injury by cleaving VWF." (PMID 39851513, 2025).
acute liver failure (9 papers, 2017 to 2026). Rapid deterioration of liver function causing encephalopathy and coagulopathy. "Targeted VWF blockade with agents such as caplacizumab may mitigate platelet loss and improve the safety profile of extracorporeal porcine liver support in acute liver failure." (PMID 41805640, 2026). "In addition, given the profound decrease in ADAMTS13 levels and specific activity, we surmise the existence of backup mechanisms to control VWF reactivity in patients with acute liver failure and advanced chronic liver disease as we and others previously proposed." (PMID 41035784, 2025). "Patients with acute liver failure and stage 3 AKI exhibited increased factor VIII and von Willebrand factor (vWF) levels, indicating endothelial activation." (PMID 40930954, 2025). "ADAMTS13:AC and VWF antigen (VWF:Ag) levels were significantly lower and higher, respectively, in patients with alcoholic hepatitis, LC, ACLF, and acute liver failure than in healthy subjects." (PMID 35407443, 2022). "Recently, the involvement of von Willebrand factor/ADAMTS13 has been suggested in thrombotic complications in liver transplantation patients, as well as a role for platelet-induced microthrombus formation in acute liver failure patients." (PMID 31717891, 2019). "Moreover, in patients with acute liver injury and acute liver failure, vWF is elevated in the serum, but could not be correlated to poor disease outcome." (PMID 34746184, 2021).